SETD2 (SET domain containing 2, histone lysine methyltransferase)
Diseases named in the same sentence as SETD2 in open-access papers (continued):
Sharing a sentence is not in itself a finding about the gene and the disease.
glioma (38 papers, 2013 to 2026). A benign or malignant brain and spinal cord tumor that arises from glial cells (astrocytes, oligodendrocytes, ependymal cells). "SETD2 is also frequently mutated or under expressed in solid tumors such as breast tumors, pediatric high-grade gliomas, lung carcinomas, gastric/pancreatic ductal adenocarcinomas, and colorectal carcinomas but also leukemia and lymphoma." (PMID 39591760, 2025). "In particular, we have defined two novel sources of ROS in gliomas: co-mutation of SETD2 in HGG and downregulation of DRG2 in LGG." (PMID 39921567, 2025). "First, we validated the association between ATRX and SETD2 mutations using the PeCan dataset for paediatric glioma (both high-grade and low-grade)." (PMID 39921567, 2025). "We identified three sources of elevated ROS in ALT-positive gliomas: co-mutation of SETD2, downregulation of DRG2, and hypoxic tumour microenvironment." (PMID 39921567, 2025). "In humans, an association was determined between high-grade gliomas and SETD2 LOF, specifically due to alterations that result in protein truncation." (PMID 38232086, 2024). "The Setd2 R1439 residue was one of the most frequently altered amino acids with missense mutations detected in 10/14 gliomas, 4/30 ENT brains and 2/9 cardiac schwannomas." (PMID 38232086, 2024). "By contrast, recent studies show that SETD2 mutations are also found in low-grade gliomas, including DAs (WHO grade II)." (PMID 35382567, 2022). "Previous research has shown that mutations of SETD2 gene frequently occur in high-grade gliomas and only occur in the area named cerebral hemispheres, and such situation is more common in children and adolescents than elderly populations." (PMID 32231741, 2020). "Recently, SETD2 was identified as tumor suppressor, as loss-of-function mutation with SETD2 has been discovered in various tumors, including ccRCC, lung adenocarcinoma, gliomas, AML, ALL, and mastocytosis." (PMID 30922329, 2019). "Missense mutations occurred throughout the SETD2 gene, and in gliomas, were found predominantly in recurrent high grade gliomas, including recurrent glioblastomas." (PMID 30419952, 2018). "Prior studies focusing on gliomas illustrate that SETD2 mutations are found nearly exclusively within the cerebral hemispheres." (PMID 30419952, 2018). "The nonsense or frameshift mutations for the low grade gliomas occurred throughout the SETD2 gene (VAF 6–34%)." (PMID 30419952, 2018). "The overexpression of H3K36me3 in cancer seems to be contradictory to the loss of function mutations of SETD2 and loss of expression of H3K36me3 in renal cell carcinoma and high-grade glioma." (PMID 30356299, 2018). "SETD2 mutations were found in high grade gliomas (n = 14, 63%), low grade gliomas (n = 3, 14%), and medulloblastomas (n = 5, 23%)." (PMID 30419952, 2018). "Prior work in gliomas also found a significant decrease in levels of H3K36me3 in gliomas with heterozygous mutations in SETD2 by Western Blot." (PMID 30419952, 2018). "Gliomas with SETD2 mutations showed significantly lower H-scores for H3K36me3 compared to wildtype controls (140.8 ± 65.4 vs. 228.8 ± 29.1, p < 0.01)." (PMID 30419952, 2018). "The detected mutations were distributed throughout SETD2 with the majority of the high grade glioma nonsense or frameshift mutations occurring 5′ to the SET domain (VAF 4–44%)." (PMID 30419952, 2018). "In gliomas, mutations have also been reported in SETD2, whose protein product is an enzyme responsible for trimethylation of the lysine 36 residue on Histone 3 (H3K36me3) in humans." (PMID 30419952, 2018).
glioma (continued). "In the 2016 WHO Classification of Tumors of the Central Nervous System, SETD2 mutations are listed under frequent genetic alterations in pediatric (but not adult) high-grade diffuse astrocytic tumors within the cerebral hemispheres." (PMID 30419952, 2018). "SET domain containing 2 (SETD2) is the major H3K36me3 methyltransferase in mammalian cells and frequently mutated in clear cell kidney carcinoma, acute leukemia, gliomas, and other cancers." (PMID 27034728, 2016). "Importantly, SETD2 CNV loss was significantly more common in ATRX-mutant glioma (14.4%) as compared to ATRX-wildtype glioma (7.9%)." (PMID 39921567, 2025). "Similarly, scRNA-seq analysis of human microglia from five glioma patients also identified a subset of high-grade glioma-associated microglial cells (HGG-AM) in IDH1-WT/SETD2-mutant GBM." (PMID 38665919, 2024). "SETD2 mutations are also present in low-grade gliomas, mainly in people aged over 55 years." (PMID 37359376, 2023). "SETD2 is also frequently mutated or under-expressed in several other cancer types including 15.9% of Phyllodes breast tumours, 15% of paediatric high grade gliomas, and 8–10% of pancreatic ductal adenocarcinomas." (PMID 37528416, 2023). "SETD2 inactivating mutations are frequently found in multiple types of cancer, including ccRCC, high-grade gliomas and leukemias." (PMID 36052643, 2022). "SETD2, a highly mutated gene, contributes to the tumorigenesis of high-grade glioma." (PMID 34212046, 2021). "SET domain containing 2 (SETD2), a major H3K36me3 methyltransferase in mammalian cells, is frequently mutated in clear cell renal carcinoma, leukemia, glioma, and other cancers, and H3K36me3 catalyzed by SETD2 is involved in mRNA alternative splicing, genome stability, and DNA repair process." (PMID 30867030, 2019). "Given the previous findings that SETD2 mutations are specific to high grade gliomas, the SETD2 change in this tumor may be hypothesized to indicate or correlate with aggressive behavior." (PMID 30419952, 2018). "Further studies are needed to assess whether this statistically significant decrease in levels of H3K36me3 in gliomas with heterozygous mutations in SETD2 has a function impact on tumorigenesis, as well as to determine if there is loss of the alternate allele." (PMID 30419952, 2018). "Our investigation of SETD2 mutations in brain tumors yields findings consistent with the previous report of SETD2 mutations in gliomas, which shows that loss-of-function SETD2 mutations occur in older children and young adults in high grade gliomas of the cerebral cortex." (PMID 30419952, 2018). "In summary, these findings suggest that SETD2 mutations, although most common in high grade gliomas of the cerebral hemispheres, may be found in a variety of primary CNS tumors and locations." (PMID 30419952, 2018). "All of these SETD2 mutations were found in GBM; four of 14 grade IV gliomas had SETD2 mutation." (PMID 28852847, 2017). "Here, we have identified loss of SETD2, dysregulation of redox genes such as DRG2 and exposure to hypoxia as sources of excessive ROS in ALT-positive gliomas." (PMID 39921567, 2025). "A subset of low-grade glioma and GBM patients harbor an inhibitory mutation in SETD2, and decreased SETD2 expression is associated with poor prognosis in GBM." (PMID 37205197, 2023). "On the other hand, the SET domain containing 2 (SETD2) was associated with a low risk of CAT across cancers, and isocitrate dehydrogenase (NADP(+)) 1 (IDH1) was associated with a low risk of CAT in glioma." (PMID 35565252, 2022).
glioma (continued). "For instance, SETD2 mutations are found in 10% of KIRC, 9% of non-small cell lung carcinomas, 15% of pediatric high-grade gliomas and 8% of adult high-grade gliomas, whereas mutations in DNMT3A are observed in over 20% acute monocytic leukemias." (PMID 30897760, 2019). "Immunohistochemical staining for H3K36me3 showed a statistically significant decrease in staining for SETD2 mutant gliomas compared to SETD2 wildtype histologic controls." (PMID 30419952, 2018). "Mutations in EGFR were found to be the most commonly co-occurring change with SETD2 changes and were seen in 40% of the high grade gliomas in this cohort, similar to the frequency of EGFR mutations found in high grade gliomas overall." (PMID 30419952, 2018). "Western blot studies have shown SETD2-mutant gliomas have decreased levels of H3K36me3, indicating that the mutations in these tumors are loss-of-function." (PMID 30419952, 2018). "SETD2 mutations are more often identified, but not exclusively, in pediatric and young adult high grade gliomas of the cerebral hemispheres." (PMID 39591760, 2025). "Importantly, H3G34 is mutated in 50 % of pediatric gliomas and H3G34V/R/D cancer driver mutations are proven to be incompatible with SETD2 substrate binding." (PMID 39591760, 2025). "In addition to the most common glioma mutations, others were detected as PPM1D mutation (3 out 10 tested samples), PIK3CA mutation (2/10 tested), BCOR mutation (1/10 tested) and SETD2 mutation in 1/10 test SCA." (PMID 35267601, 2022). "SETD2 mutations were seen in both low and high grade gliomas as well as non-glial tumors, and occurred in patients greater than 55 years of age, in addition to pediatric and young adult patients." (PMID 30419952, 2018). "In total, 23 SETD2 changes amongst the 19 tumors were detected at a wide range of VAF (range 2–51%); 4 tumors had more than one SETD2 missense mutation, 3 of which were recurrent high grade gliomas, and the fourth a medulloblastoma." (PMID 30419952, 2018). "In contrast to previous work showing that SETD2 mutations are seen in high grade gliomas but not low grade gliomas, we found frameshift mutations in SETD2 in two diffuse astrocytomas, WHO grade II." (PMID 30419952, 2018). "Indeed, co-mutant EGFR and SETD2 are common in glioma and pan-cancer, suggesting that SETD2-mutant cancer might have evolved a unique dependence on EGFR signaling." (PMID 32824422, 2020). "The frequency of SETD2 mutation (24%, 4/17) in DCGs was significantly higher than those in previous large-scale genetic analyses of adult gliomas, which showed a SETD2 mutation rate of 1.7% in GBM (5/292, p = 0.0007) and 2.1% in lower-grade glioma (3/283, p = 0.0002)." (PMID 28852847, 2017). "We note that two of 10 individuals with a SETD2 NDD reported here had developed a tumor (a sarcoma in one case and multiple gliomas in the other)." (PMID 37166351, 2023). "We observed a significantly higher TMB level in SETD2 mut + in colorectal cancer (P < 0.001), NSCLC (P < 0.001), melanoma (P = 0.0022), glioma (P = 0.0042), and pancreatic cancer (P = 0.00012)." (PMID 37479966, 2023). "Microglia in mutant SETD2 (SETD2-mut)/IDH-WT GBM exhibit pro-inflammatory and proliferative phenotypes probably through stimulation of glioma-derived TGF-β1 expression via the apolipoprotein E (ApoE)-mediated NLRP1 inflammasome." (PMID 36555253, 2022).
glioma (continued). "This was particularly surprising for Setd2 given that it was altered in every glioma and cardiac schwannoma in this study, with only one nonsense mutation (SETD2 p158R> *) reported in the COSMIC database." (PMID 38232086, 2024). "While Setd2 variant in one cardiac schwannoma was described in COSMIC, none of the Setd2 variants in gliomas were in the database." (PMID 38232086, 2024). "Selective targeting of H3K4 and H3K36 methylation by oncogenic mutations was also observed in other studies that are not yet available from TCGA; for instance, mutations in SETD2 and genes affecting H3K36 methylation are recurrent in high-grade gliomas." (PMID 25484917, 2014). "In these recurrent/residual high grade gliomas with changes in SETD2, longer durations of follow-up were seen after initial presentation (mean of 79 and 42 months for IDH-mutant tumors and 52.5 ± 12.0 months for IDH-wildtype tumors) than is common for high grade gliomas." (PMID 30419952, 2018). "Indeed, genetic alterations in EGFR and SETD2 frequently co-occur in glioma and TCGA pan-cancer cohort, supporting the notion that co-occurring EGFR and SETD2 alterations cooperate to promote tumor progression, and that SETD2-mutant cancer may evolve a dependency on EGFR signaling." (PMID 32824422, 2020).
lung adenocarcinoma (38 papers, 2013 to 2025). A carcinoma that arises from the lung and is characterized by the presence of malignant glandular epithelial cells. "Although understudied, SETD2 inactivation has been implicated in the tumorigenesis of a wide variety of cancers, including lung adenocarcinoma." (PMID 41228333, 2025). "Future study is warranted on both patient outcomes and immunopathologic characteristics of SETD2-mutated lung adenocarcinoma." (PMID 41228333, 2025). "The goal of this study is to elucidate the characteristics and prognosis of SETD2-mutated lung adenocarcinoma." (PMID 41228333, 2025). "Deletions and/or loss-of-function mutations in SETD2 are also detected recurrently in different types of leukemia and solid tumors including gastroesophageal cancers and lung adenocarcinoma (LUAD), though at lower frequency than seen in ccRCC." (PMID 40462961, 2025). "With the largest cohort to date, we describe the clinical characteristics and molecular profiles of SETD2-mutated lung adenocarcinoma from a large cohort of patients at a single institution." (PMID 41228333, 2025). "Of 500 consecutive patients seen between October 2018 and 4 January 2020, 174 non-SETD2-mutated lung adenocarcinomas met inclusion criteria." (PMID 41228333, 2025). "As previously discussed, in lung adenocarcinoma a loss of SETD2 favors cell proliferation, migration, invasion and EMT through regulation of the STAT1–IL-8 signaling pathway." (PMID 39591760, 2025). "Secondarily, we define the clinical and molecular characteristics of SETD2-mutated lung adenocarcinoma and demonstrate that SETD2-mutated tumors have a unique genetic profile." (PMID 41228333, 2025). "Herein, with the largest clinical cohort to date, we demonstrate that SETD2-mutated lung adenocarcinoma presents at a significantly earlier stage and trends towards improved recurrence-free survival in early-stage tumors." (PMID 41228333, 2025). "With the largest cohort of SETD2-mutated lung adenocarcinoma to date, we demonstrate that SETD2 mutation is associated with a presentation at an earlier stage and trends towards an association with improved recurrence-free survival." (PMID 41228333, 2025). "With the largest cohort to date, we demonstrate that SETD2-mutated lung adenocarcinoma presents at significantly earlier stages, has a unique molecular profile compared to non-mutated tumors, and trends towards improved RFS in early-stage tumors." (PMID 41228333, 2025). "These last processes would be caused in lung adenocarcinoma by the negative regulation of IL-8 transcription in a STAT1-dependent manner relying on SETD2 trimethylation of H3K36." (PMID 39591760, 2025). "The effect of SETD2 mutations on ferroptosis has broader disease implications as SETD2 mutations occur in ~10% of lung adenocarcinomas." (PMID 40961184, 2025). "With the largest cohort to date, we aim to elucidate the clinicopathologic characteristics and prognosis of SETD2-mutated lung adenocarcinoma." (PMID 41228333, 2025). "Several elegant previous in vivo studies utilizing either CRISPR-based or gene knockout approaches demonstrated that loss of SETD2 promotes lung adenocarcinoma (LUAD) tumorigenesis in the canonical KRASG12D-driven LUAD mouse tumor model." (PMID 40462961, 2025). "Remarkably, both mouse lung tumors and human lung adenocarcinomas from TCGA data set showed highly enriched PRC2 signature in tumors with SETD2 loss." (PMID 36810256, 2023). "Based on The Cancer Genome Atlas Lung Adenocarcinoma (TCGA-LUAD) data set, SETD2 is the eighth most commonly mutated gene and the most frequently mutated epigenetic modifier in lung adenocarcinoma." (PMID 36810256, 2023). "SETD2 loss promoted progression in early- and late-stage lung adenocarcinoma in a KRASG12D-driven mouse model." (PMID 38036730, 2023).